LINCMD1 (long independently transcribed non-coding RNA, muscle differentiation 1)
Synonyms: formerly MIR133BHG; LINC-MD1
Gene: Long non-coding RNA gene on chromosome 6 (52,146,814 to 52,151,119, reverse strand). Ensembl gene ENSG00000225613.
Diseases named in the same sentence as LINCMD1 in open-access papers:
LINCMD1 is named in the same sentence as 8 diseases in open-access papers, as found by Europe PMC text mining. Sharing a sentence is not in itself a finding about the gene and the disease. The quoted sentences say what the papers report.
leiomyoma (1 paper, 2024). A well-circumscribed benign smooth muscle neoplasm characterized by the presence of spindle cells with cigar-shaped nuclei, interlacing fascicles, and a whorled pattern. "Next, we investigated the functional relationship between LINCMD1 and miR-135b in leiomyomas, given their inverse expression pattern." (PMID 39519092, 2024). "The decreased expression of LINCMD1 in leiomyoma tissue leads to an increase in miR-135b levels, which subsequently downregulates its target gene, APC." (PMID 39519092, 2024). "This study investigated LINCMD1′s involvement in leiomyoma by analyzing paired myometrium and leiomyoma tissue samples (n = 34) from patients who had not received hormonal treatments for at least three months prior to surgery." (PMID 39519092, 2024). "Using qRT-PCR, we confirmed that LINCMD1 is expressed in both leiomyomas and matched myometrium, but at significantly lower levels in leiomyomas." (PMID 39519092, 2024). "To explore the relationship between LINCMD1 and these miRNAs in leiomyomas, we first assessed their expression levels." (PMID 39519092, 2024). "This mechanistic insight provides a promising foundation for targeting non-coding RNAs, such as LINCMD1, to correct the abnormal activation of the Wnt/β-Catenin pathway, and as a potential therapeutic target for leiomyomas." (PMID 39519092, 2024). "In this study, we hypothesized that leiomyomas express lower levels of LINCMD1 compared to the myometrium and that LINCMD1, through a miR-135-guided mechanism, regulates the expression of genes associated with Wnt/β-Catenin signaling activation." (PMID 39519092, 2024). "Existing evidence indicates that LINCMD1 regulates muscle differentiation-related gene expression in skeletal muscle by acting as a miRNA sponge, though its role in leiomyoma development is still unknown." (PMID 39519092, 2024). "Our data indicate that LINCMD1 functions as a molecular sponge for the miR-135b in leiomyomas." (PMID 39519092, 2024). "The results showed that leiomyoma tissues had significantly reduced LINCMD1 mRNA levels, regardless of patient race or MED12 mutation status, while miR-135b levels were elevated compared to matched myometrium samples." (PMID 39519092, 2024). "Additionally, we observed a correlation between elevated COL1A1 expression and decreased LINCMD1 levels in leiomyomas, which could be reversed by correcting miR-135b levels." (PMID 39519092, 2024). "In conclusion, our study uncovers a novel regulatory axis involving the long non-coding RNA LINCMD1 and miR-135b, which modulates the Wnt/β-Catenin signaling pathway and contributes to ECM deposition in leiomyomas." (PMID 39519092, 2024).
lung adenocarcinoma (1 paper, 2024). A carcinoma that arises from the lung and is characterized by the presence of malignant glandular epithelial cells. "LINCMD1 (Long Intergenic Non-Protein Coding RNA, Muscle Differentiation, MIR133BHG) (average methylation 80%, p = 0.01) inhibits cell proliferation, migration, and the invasion of lung adenocarcinoma." (PMID 38791918, 2024).
cancer (2 papers, 2020 to 2024). A tumor composed of atypical neoplastic, often pleomorphic cells that invade other tissues. "In addition to LINCMD1, several lncRNAs have been identified as modulators of the Wnt/β-Catenin signaling pathway, which could contribute to cancer prognosis and diagnosis." (PMID 39519092, 2024).
tumor (1 paper, 2024). "PD-L1 high-expressing tumors show hypermethylated genes and promoters with strong oncogenic effects (SNORD114-14, DCAF4L2, S100A7L2, and SOD1P3) and hypermethylated genes and promoters with tumor suppressor effects (CELF2-AS1 and LINCMD1)." (PMID 38791918, 2024). "On the other hand, hypermethylated genes and promoters in the PD-L1 high-expression group have suppressor effects (CELF2-AS1, LINCMD1, and MIR133BHG), which appear ineffective in reducing tumor progression compared to this group’s simultaneously activated dominant oncogenic mechanisms." (PMID 38791918, 2024).
LINCMD1 also shares sentences with these, for which no sentence is quoted: Duchenne muscular dystrophy (4 papers); Cachexia (1); muscle disorder (1); sarcopenia (1).